ENSG00000273782
Gene: Miscellaneous RNA gene on chromosome 19 (15,834,730 to 15,834,804, forward strand). Ensembl gene ENSG00000273782.
Gene Ontology:
Biological process: regulation of gene expression